BPGM (bisphosphoglycerate mutase)
Description:
Plays a major role in regulating hemoglobin oxygen affinity by controlling the levels of its allosteric effector 2,3-bisphosphoglycerate (2,3-BPG). Also exhibits mutase (EC 5.4.2.11) activity.
Synonyms: DPGM; ECYT8
Tractability: Small molecule: a structure with a bound ligand is known; it has a high-quality binding pocket. PROTAC: ubiquitination databases record sites on it; its protein half-life has been measured.
Target class: Isomerase; Enzyme
Gene: Protein-coding gene on chromosome 7 (134,646,811 to 134,679,816, forward strand). Ensembl gene ENSG00000172331.
Subcellular location (Human Protein Atlas): Nucleoli; Nucleoli rim; Nucleoplasm
Pathways (Reactome):
Metabolism: Glycolysis
Gene Ontology:
Molecular function: protein binding; bisphosphoglycerate mutase activity; catalytic activity; intramolecular phosphotransferase activity; phosphoglycerate mutase activity
Biological process: carbohydrate derivative catabolic process; carbohydrate metabolic process; respiratory gaseous exchange by respiratory system; glycolytic process
Cellular component: extracellular exosome; cytosol
Genetic constraint (gnomAD): Loss-of-function variants: 15 observed, 23.4 expected, observed/expected ratio (o/e) 0.64, 90% interval 0.43 to 0.99. The upper end of that interval is the gene's LOEUF score, 0.99, which puts it in group 4 of 6, group 1 being the genes least tolerant of losing a copy. Missense variants: 273 observed, 334.49 expected, observed/expected ratio (o/e) 0.82, 90% interval 0.74 to 0.9. Synonymous variants: 113 observed, 123.04 expected, observed/expected ratio (o/e) 0.92, 90% interval 0.79 to 1.07.
Homologues: Orthologues: chimpanzee BPGM (99% identical), macaque BPGM (99% identical), pig BPGM (97% identical), rabbit BPGM (97% identical), guinea pig BPGM (95% identical), mouse Bpgm (92% identical), rat Bpgm (90% identical), tropical clawed frog bpgm (77% identical), zebrafish bpgm (73% identical), Drosophila melanogaster CG7059 (41% identical). Paralogues in human: PGAM1 (53% identical), PGAM4 (51% identical), PGAM2 (51% identical).
Diseases named in the same sentence as BPGM in open-access papers:
BPGM is named in the same sentence as 24 diseases in open-access papers, as found by Europe PMC text mining. Sharing a sentence is not in itself a finding about the gene and the disease. The quoted sentences say what the papers report.
Sepsis (3 papers, 2024 to 2025). Sepsis is defined as life-threatening organ dysfunction caused by a dysregulated host response to infection. "In a study involving 306 patients with sepsis, four subtypes were established, with Mars 1 having the most severity and highest mortality rate; this subtype was associated with specific genes (BPGM and TAP2)." (PMID 40504881, 2025). "Kaplan–Meier analysis showed that serum BPGM-positive sepsis patients had a significantly shorter 28-day survival time (p < 0.001)." (PMID 38326761, 2024). "This study aims to investigate the value of bisphosphoglycerate mutase (BPGM), an intermediate in the glycolytic pathway, in evaluating cardiac injury in septic patients and predicting poor prognosis in sepsis." (PMID 38326761, 2024). "Our findings suggest that serum BPGM positivity is an independent risk factor for sepsis-related 28-day mortality and that the level of serum BPGM levels is a useful indicator for evaluating cardiac function impairment and prognosis in sepsis patients." (PMID 38326761, 2024). "Consequently, this might contribute to the higher 28-day mortality rate in septic myocardial disease, which could denote a distinct aspect of glycolytic pathway alteration compared to sepsis alone, suggesting BPGM as a potential diagnostic or therapeutic target for septic myocardial disease." (PMID 38326761, 2024). "However, the 28-day mortality in the positive group was significantly higher than that in the negative group (5 vs. 19; p < 0.001), indicating poor prognosis in sepsis patients with high serum BPGM levels." (PMID 38326761, 2024). "According to previous studies, BPGM is an important intermediate in regulating the glycolytic process, which can directly regulate the generation of 1,3-BPG to 2,3-BPG, affecting the glycolysis rate, and may affect the energy metabolism of sepsis." (PMID 38326761, 2024).
Acidosis (1 paper, 2021). Abnormal acid accumulation or depletion of base. "The main objective of the study conducted here was to estimate the concentration of 2,3‐Bisphosphoglycerate (2,3‐BPG), 1,3‐Bisphosphoglycerate (1,3‐BPG), bisphospho‐glycerate mutase (BPGM) and 3‐phosphoglycerate (3PG) in cattle clinically diagnosed with acute ruminal acidosis." (PMID 34273253, 2021).
acute kidney injury (1 paper, 2025). Sudden and sustained deterioration of the kidney function characterized by decreased glomerular filtration rate, increased serum creatinine or oliguria. "We, therefore, assumed that upregulation of BPGM in acute kidney injury (AKI) might be protective by moderating excessive glycolytic flux, especially under hypoxia or cellular stress." (PMID 39422260, 2025).
anemia (1 paper, 2022). A reduction in the number of red blood cells, the amount of hemoglobin, and/or the volume of packed red blood cells. "In addition, the potentially related diseases to specific patients’ proteins were anemias or hematopoietic system diseases (proteins HBZ, EPB41, HP, PGK1, HBE1, BPGM, and ALDOA)." (PMID 36519745, 2022).
cardiac hypertrophy (1 paper, 2024).
chronic kidney disease (1 paper, 2022). Impairment of the renal function secondary to chronic kidney damage persisting for three or more months. "BPGM (Bisphosphoglycerate Mutase), a small molecule found at high concentrations in red blood cells where it binds to and decreases the oxygen affinity of hemoglobin, is associated with erythrocyte metabolic reprogramming in chronic kidney disease." (PMID 35154510, 2022).
hepatocellular carcinoma (1 paper, 2026). A malignant tumor that arises from hepatocytes. "Aerobic glycolysis is a hallmark of cancer, yet the role of the key glycolytic enzyme bisphosphoglycerate mutase (BPGM) in hepatocellular carcinoma (HCC) progression remains unclear." (PMID 41514495, 2026).
lymphoma (1 paper, 2023). A malignant (clonal) proliferation of B- lymphocytes or T- lymphocytes which involves the lymph nodes, bone marrow and/or extranodal sites. "No expression difference was found of ALDH2, ANGPTL4, BPGM, and PAM between lymphoma patients and control samples." (PMID 36755971, 2023).
renal carcinoma (1 paper, 2026). A carcinoma arising from the epithelium of the renal parenchyma or the renal pelvis. "Our data identify BPGM as a metabolic player contributing to stress-adaptive transcriptional states in ccRCC and suggest that targeting metabolic stress adaptation may complement epigenetic strategies in renal cancer." (PMID 41972721, 2026).
RSV bronchiolitis (1 paper, 2021). "A previous study reported that gene expression of BPGM is significantly upregulated in infants with RSV bronchiolitis." (PMID 33656056, 2021).
cancer (6 papers, 2011 to 2026). A tumor composed of atypical neoplastic, often pleomorphic cells that invade other tissues. "Additionally, the biological function of FNDC3B and BPGM in regulating cancer cell proliferation, invasion, and therapy resistance needs to be clarified." (PMID 34976823, 2021). "BPGM was reported to control serine flux via 3-phosphoglycerate, which may benefit cancer cell survival." (PMID 31847435, 2019).
infection (3 papers, 2020 to 2024). The state of being infected such as from the introduction of a foreign agent such as serum, vaccine, antigenic substance or organism. "It was reported that the BPGM gene expression was significantly upregulated in some form of inflammation and infection." (PMID 37393262, 2023). "In infected HFF cells, bisphosphoglycerate mutase (BPGM), the main source of 2,3-BPG, is transcriptionally upregulated during the first twelve hours of infection." (PMID 32255806, 2020).
tumor (3 papers, 2020 to 2026). "We investigated the role of the glycolytic enzyme 2,3-bisphosphoglycerate mutase (BPGM) using human tumor specimens, siRNA-mediated gene silencing, functional cell-based assays, and transcriptomic profiling." (PMID 41972721, 2026).
renal diseases (1 paper, 2016). "Among the 148 identified mRNAs, BPGM is unregulated in ChRCC, some mRNAs have been reported to be associated with renal diseases." (PMID 27258182, 2016).
BPGM also shares sentences with these, for which no sentence is quoted: bladder cancer (1 paper); cervical cancer (1); colon adenocarcinoma (1); erythrocytosis (1); hematopoietic system diseases (1); hemoglobinopathies (1); myeloma (1); myocardial disease (1); polycythaemia vera (1); thyroid tumours (1).